ADSS1 (adenylosuccinate synthase 1)
Description:
Component of the purine nucleotide cycle (PNC), which interconverts IMP and AMP to regulate the nucleotide levels in various tissues, and which contributes to glycolysis and ammoniagenesis. Catalyzes the first committed step in the biosynthesis of AMP from IMP.
Synonyms: AdSSL1; FLJ38602; MPD5
Tractability: PROTAC: ubiquitination databases record sites on it.
Gene: Protein-coding gene on chromosome 14 (104,724,174 to 104,747,325, forward strand). Ensembl gene ENSG00000185100.
Subcellular location: Cytoplasm
Pathways (Reactome):
Metabolism: Purine ribonucleoside monophosphate biosynthesis
Gene Ontology:
Molecular function: adenylosuccinate synthase activity; protein binding; GTP binding; phosphate ion binding; magnesium ion binding; nucleotide binding
Biological process: AMP biosynthetic process; 'de novo' AMP biosynthetic process; immune system process; IMP metabolic process; AMP salvage; purine nucleotide biosynthetic process
Cellular component: cytoplasm; cytosol
Genetic constraint (gnomAD): Loss-of-function variants: 54 observed, 54.43 expected, observed/expected ratio (o/e) 0.99, 90% interval 0.8 to 1.25. The upper end of that interval is the gene's LOEUF score, 1.25, which puts it in group 5 of 6, group 1 being the genes least tolerant of losing a copy. Missense variants: 580 observed, 573.25 expected, observed/expected ratio (o/e) 1.01, 90% interval 0.94 to 1.08. Synonymous variants: 241 observed, 231.65 expected, observed/expected ratio (o/e) 1.04, 90% interval 0.94 to 1.16.
Homologues: Orthologues: mouse Adss1 (97% identical), guinea pig ADSS1 (96% identical), dog ADSS1 (95% identical), pig ADSS1 (90% identical), chimpanzee ADSS1 (89% identical), tropical clawed frog adss1 (88% identical), rat Adss1 (86% identical), zebrafish adss1 (80% identical), macaque ADSS1 (77% identical), rabbit ADSS1 (62% identical), Drosophila melanogaster Adss (60% identical), Caenorhabditis elegans adss-1 (50% identical). Paralogues in human: ADSS2 (75% identical).
Diseases named in the same sentence as ADSS1 in open-access papers:
ADSS1 is named in the same sentence as 16 diseases in open-access papers, as found by Europe PMC text mining. Sharing a sentence is not in itself a finding about the gene and the disease. The quoted sentences say what the papers report.
Obesity (2 papers, 2022 to 2026). Accumulation of substantial excess body fat. "Collectively, these findings strongly suggest that, in human adipose tissue, ADSS1 may play a causal role in the pathogenesis of obesity and its associated metabolic dysfunctions." (PMID 41117143, 2026). "Adipose‐specific Adss1 knockout mice showed increased energy expenditure and resistance to diet‐induced obesity with improved metabolic dysfunction." (PMID 41117143, 2026). "Taken together, these findings indicate that Adss1 deletion enhances energy expenditure and protects against diet‐induced obesity." (PMID 41117143, 2026). "To investigate the clinical relevance of ADSS1 in obesity, we analyzed adipose tissue samples from lean, overweight, and obese individuals." (PMID 41117143, 2026). "Having established that conditional ablation of Adss1 enhances whole‐body energy expenditure in CD‐fed mice, we next examined whether Adss1AKO mice were protected from diet‐induced obesity." (PMID 41117143, 2026).
congenital myopathy (1 paper, 2026). "ADSS1 myopathy is an ultrarare congenital myopathy characterized by progressive cardiac and skeletal muscle degeneration with childhood to adolescent onset." (PMID 41263703, 2026).
liver disease (1 paper, 2026). "Moreover, ADSS1 expression was negatively correlated with liver disease markers, including AST and ALT." (PMID 41117143, 2026).
myopathy (7 papers, 2022 to 2026). A disease of the muscle in which the muscle fibers do not function properly. "ADSS1 myopathy (previously referred to as ADSSL1 myopathy) is a rare autosomal recessive muscle disease caused by mutations in the ADSS1 gene, which encodes an enzyme critical for purine nucleotide synthesis." (PMID 41973717, 2026). "and Dr Linlin Wan, M.D., presented on the metabolomic profiles of ADSS1 deficient mice and patients providing unique insight into the ADSS1 myopathy disease signature in blood and muscle." (PMID 39593137, 2024). "Understanding the cause of weakness in ADSS1 myopathy is necessary." (PMID 39593137, 2024). "Consequently, Dr. Park’s team hypothesised loss of ADSS1 function and purine homeostasis to be the cause of myopathy." (PMID 39593137, 2024). "With a limited patient profile encompassing fewer than 200 known patients worldwide, establishing a mouse model for ADSS1 myopathy is critical to understanding its pathogenesis and for developing future therapies." (PMID 41263703, 2026). "Transcriptome analysis of skeletal muscle biopsies from ADSS1 myopathy patients revealed significant downregulation of all three purine nucleotide cycle (PNC) genes: ADSS1, adenylosuccinate lyase (ADSL) and adenosine monophosphate deaminase 1 (AMPD1)." (PMID 39593137, 2024). "Relative to heterozygous controls, patients with ADSS1 myopathy demonstrated lower phase and reactance values at 100 kHz, while muscle resistance was higher, which together points to the presence of diseased muscle tissue in the ADSS1 cohort." (PMID 39593137, 2024). "The meeting addressed the current state of knowledge and research needs concerning ADSS1 myopathy pathogenesis, clinical presentation, biomarker discovery and therapeutic development." (PMID 39593137, 2024). "Adenylosuccinate synthetase 1 (ADSS1) myopathy is an ultra-rare, slowly progressive neuromuscular disease (NMD) leading to progressive deterioration and loss of function of skeletal and cardiac muscles." (PMID 39593137, 2024). "Understanding in which contexts these metabolites are affected in ADSS1 myopathy, and whether alterations are a primary driver of myopathy, requires intensive study." (PMID 39593137, 2024). "Slow-twitch oxidative muscle could be predominantly impacted if reactive oxygen species are driving pathology in ADSS1 myopathy." (PMID 39593137, 2024). "Allopurinol and febuxostat are clinically utilised XOR inhibitors that could be useful for ADSS1 myopathy to stem this excretion." (PMID 39593137, 2024). "ADSS1 deficient iPSC lines have been created from two ADSS1 myopathy siblings, a non-diseased familial control, and isogenic variants introduced via CRISPR mutation." (PMID 39593137, 2024). "There was also focused discussion on whether exercise might exacerbate ADSS1 myopathy." (PMID 39593137, 2024). "Therapeutic development for ADSS1 myopathy could take many approaches." (PMID 39593137, 2024). "Cure ADSSL1 is the only organisation worldwide exclusively focused on supporting and advancing treatments for ADSS1 myopathy patients." (PMID 39593137, 2024).
ADSS1 also shares sentences with these, for which no sentence is quoted: Distal myopathies (2 papers); malaria (2); cancer (1); cardiomyopathy (1); filaminopathy (1); glioblastoma (1); Intellectual disability (1); metabolic disorders (1); myocardial infarction (1); myotilinopathy (1); Treacher-Collins syndrome (1); tumour (1).